TYK2 (tyrosine kinase 2)
Diseases named in the same sentence as TYK2 in open-access papers (continued):
Sharing a sentence is not in itself a finding about the gene and the disease.
COVID-19 (continued). "We identified five common feature genes (DHX15, USP14, COPS3, TYK2, and RIOK2) and their co-regulatory pathways between T2DM and COVID-19, which may provide new insights for molecular mechanism studies." (PMID 38699234, 2024). "We identified five common feature genes (DHX15, USP14, COPS3, TYK2, and RIOK2) and their co-regulatory pathways between T2DM and COVID-19, which may provide new insights for further molecular mechanism studies." (PMID 38699234, 2024). "In the validation dataset, the AUC values of DHX15, USP14, COPS3, TYK2, and RIOK were 0.922, 0.781, 0.812, 0.844, and 0.984, respectively, for T2DM, and 0.733, 0.687, 0.737, 0.782, and 0.632, respectively, for COVID-19." (PMID 38699234, 2024). "The results from the ROC curve analysis showed that DHX15, USP14, COPS3, TYK2, and RIOK had AUC values of 0.931, 0.917, 0.986, 0.903, and 0.917, respectively, for T2DM and AUC values of 0.960, 0.860, 1.0, 0.9, and 0.90, respectively, for COVID-19." (PMID 38699234, 2024). "The roles of DHX15, USP14, COPS3, TYK2, and RIOK2 in T2DM and COVID-19 remain primarily unknown, emphasizing the importance of future research." (PMID 38699234, 2024). "Our study did not establish that the expressions of IFNAR2 and TYK2 genes serve as a predictor of severity of COVID-19, likely due to limitations such as small sample size." (PMID 39351231, 2024). "Based on our findings, the negative correlation between IFNAR2 and TYK2 expression levels, even after adjusting for confounding factors, highlights their potential role in COVID-19 pathogenesis." (PMID 38741892, 2024). "Notably, tofacitinib, the inhibitor drug targeting TYK2, is indicated for the treatment of ulcer colitis (a subtype of IBD), while baricitinib, also targeting TYK2, is approved for the treatment of COVID-19." (PMID 38102678, 2023). "All signaling molecules of the IFN-I downstream pathway and IRFs (i.e., JAK-1, TYK-2, STAT-1, STAT-2, IRF-3, and IRF-7) showed very reduced expression levels in COVID-19 patients with the severe condition compared to healthy individuals at both RNA and protein levels." (PMID 35842705, 2022). "Inhibits JAK3, JAK1, JAK2, and to a lesser extent TYK2 and inhibits receptor signaling through pairs of JAK2 and because it can suppress the production of different cytokines, such as IL-2, IL-7 and IL-6 can used for patients with COVID-19." (PMID 36111104, 2022). "stated that, although TYK2 expression was suppressed in Iranian COVID-19 patients compared to controls, TYK2 levels could not differentiate properly between non-ICU and ICU admitted patients." (PMID 41445728, 2025). "However, neither IFNAR2 nor TYK2 expression was significantly different between the case subgroups based on COVID-19 severity." (PMID 38741892, 2024). "In addition to this mechanism, it has recently been highlighted that androgen suppression of TYK2 (member of the Janus Kinase, JAK, family of genes) signalling in T lymphocytes may be an important determinant of COVID-19 outcome." (PMID 38307934, 2024). "In good concordance with these previous results, we found TYK2 gene expression elevated in PBCs of COVID-19 patients on hospital admission, with a (non-significant) trend to higher levels in those that developed critical illness during hospitalization, and independent of the patient BMI range." (PMID 36009555, 2022). "Therefore, based on our study, TYK2 did not impact COVID-19 outcome or the autoimmune regulatory mechanism that can be defined in MIS-C, but studies are ongoing, and other regulatory pathways could be found." (PMID 37896870, 2023).
viral infections (50 papers, 2011 to 2025). "Subsequent studies in 2004 revealed a novel autosomal recessive form of HIES in consanguineous families, whereas in 2006, a deficiency in tyrosine kinase 2 (TYK2) was linked to susceptibility to intracellular bacterial and viral infections in AR-HIES patients." (PMID 40688464, 2025). "Exposure of naïve CD8 T cells to type I interferons causes fast transformation of these cells to effector cells, and still provides a proper response to viral infection even in carriers of the TYK2:p.Pro1104Ala variant." (PMID 39835539, 2025). "The cellular response to type III IFN of these AR TYK2-deficient patients appears to be maintained, and responses to type I IFNs are only partially affected, and only in patients with complete or partial TYK2 deficiency, 60% of whom had viral disease." (PMID 36719370, 2023). "We can validate these findings in humans and move closer to a personalized medicine approach, possibly by topically delivering JAKi selective for JAK1/TYK2 to individuals at greatest risk for life-threatening viral diseases." (PMID 37298195, 2023). "IL12RB1, a subunit of the interleukin 12 receptors is associated with tyrosine kinase 2 (TYK2), which plays a pivotal role in immunity to viral infection and cancer surveillance." (PMID 37228491, 2023). "Four of these 19 patients with biallelic TYK2 variants presented only intramacrophagic infections, six had viral diseases only, seven had combinations of viral, mycobacterial, and fungal diseases, and two were asymptomatic." (PMID 36094518, 2022). "On the other hand, AR complete TYK2 deficiency result in susceptibility to mycobacterial and viral disease as a result of impaired signaling from the IL-12/IL-23/IL-10 and IFN-α/β receptors respectively." (PMID 36159783, 2022). "We studied the cellular basis of mycobacterial and viral diseases in TYK2-deficient patients by studying peripheral blood mononuclear cells (PBMCs) from P-Tur (L767*/L767*), P1 (C70Hfs*21/C70Hfs*21), and P11 (P216Rfs*14/P216Rfs*14)." (PMID 36094518, 2022). "We set out to discover new genetic and immunological forms of AR TYK2 deficiency by searching for biallelic TYK2 variants in patients with mycobacterial or viral diseases." (PMID 36094518, 2022). "Humans with complete TYK2 loss of function have clinically significant immunodeficiency with increased susceptibility to mycobacterial and viral infections." (PMID 35482673, 2022). "Sensitive SJL/J mice are known to have mutations in the tyrosine kinase 2 (Tyk2) gene associated with the capacity of interferon-dependent defense, an important part of innate immunity against viral infections." (PMID 36421377, 2022). "The 25 known patients with complete TYK2 deficiency (including 15 previously reported and 10 reported herein) have suffered from intramacrophagic infections (mostly due to mycobacteria) or viral infections (mostly due to herpesviruses) or both." (PMID 36094518, 2022). "While mycobacteria infections were not reported in the trials of deucravacitinib, there was a higher incidence of respiratory and nasopharyngeal infections, indicating enhanced susceptibility to viral infection as an adverse event to TYK2 blockade." (PMID 34290741, 2021). "Clinical appearances of TYK2 deficiency are typically mycobacterial and/or viral infections, caused by impaired responses to IL-12 and IFN-α/β." (PMID 34439323, 2021). "While TYK2 deficiency is accompanied by recurrent viral and bacterial infections, elevated TYK2 activity is also connected with complications of viral infections." (PMID 34439323, 2021). "People naturally deficient in TYK2 have increased sensitivity to mycobacterial and viral infections." (PMID 34234812, 2021). "One patient with complete TYK2 deficiency suffered from frequent bacterial and viral infections as well as HIES-like disease." (PMID 34439323, 2021). "Deficiency in TYK2 is associated with Immunodeficiency 35 phenotype and increasing susceptibility to viral infection (OMIM#611521)." (PMID 33815474, 2021).
viral infections (continued). "The recessive form, characterized by viral infections and neurologic complications, has been linked to TYK2 deficiency; however, the genetic cause is still under investigation." (PMID 34439323, 2021). "Based on this patient, our previous studies found that the expression levels of Tyk2 protein and gene were decreased by c.2395G>A mutation, so his susceptibility to mycobacterial and viral infections was well explained." (PMID 34234812, 2021). "The study suggested that the susceptibility to intracellular bacterial and/or viral infections identified in all the TYK2-deficient patients was caused by impaired responses to IL-12 and type I IFN14." (PMID 29725107, 2018). "It was suggested that the important clinical phenotypes of TYK2 deficiency is mainly mycobacterial and/or viral infections caused by impaired IL-12 and IFN-alpha/beta responses, but not elevated IgE levels." (PMID 28826655, 2017). "We first screened human TYK2 gene polymorphisms in 22 patients with T1D associated with flu-like syndrome, suggestive of possible viral infection, by PCR amplification followed by direct sequencing." (PMID 26288847, 2015). "Second-generation JAKi, such as filgotinib, itacitinib, and upadacitinib (anti JAK1), fedratinib (anti JAK2), and deucravacitinib (anti TYK2) offer greater target specificity and may provide a lower risk for hematological abnormalities and viral infections." (PMID 41438753, 2025). "JAK3 and TYK2 mediate a smaller number of signaling pathways, and human deficiencies are less severe, with effects predominantly being on the arms of the immune system and/or associations with specific bacterial and viral infections." (PMID 40103808, 2025). "TYK2 loss-of-function genes are associated with protection against axSpA, and TYK2 deficiency may lead to increased susceptibility to mycobacterial/viral infections." (PMID 40103808, 2025). "We searched for biallelic variants, including at least one very rare or rare (frequencies <0.01 and <1%, respectively, in the general population) nonsynonymous or essential splice site variant of TYK2 (NM_003331) by WES in patients with unexplained mycobacterial or viral diseases." (PMID 36094518, 2022). "Therefore, the possibility of TYK2 deficiency should be considered when a patient has repeated intracellular bacteria (including tuberculosis bacillus infection), repeated viral infection or eczema." (PMID 32537443, 2020). "Yet, in the case of fulminant T1D caused by viral infection, high TYK2 in pancreatic β cells may be protective by mediating a robust IFN-mediated antiviral response." (PMID 31961910, 2020). "Thus, the observation seems to be consistent with our previous report that TYK2 promoter variant was most likely associated with viral infections in diabetic patients dependent on defective type 1 IFN response, but not with Th2 immune response." (PMID 28826655, 2017). "Therefore unknown factors associated with the TYK2 promoter variant other than viral infection may also contribute to increase the risk for diabetes." (PMID 26288847, 2015). "Deficiency of TYK2, classified as Immunodeficiency-35 (IMD35), is an autosomal recessive disorder typified by increased vulnerability to mycobacterial and viral infections, recurrent respiratory disease, and in select cases elevated serum IgE levels." (PMID 41465118, 2025). "Background/Objectives: Hereditary anomalies in the TYK2 gene are the basis of a rare primary immunodeficiency, immunodeficiency-35, typified by an augmented vulnerability to mycobacterial and viral infections." (PMID 41465118, 2025). "The viral infection also hinders IFN type I by preventing the phosphorylation of tyrosine kinase 2 (TYK2) and inhibiting the activation of STAT1 and STAT2." (PMID 37242305, 2023). "LOF mutations in STAT1 and TYK2 increase susceptibility to bacterial and viral infections, while LOF in STAT2 increases the incidence of viral infections and LOF in STAT4 increases the incidence of fungal infections." (PMID 35337171, 2022).
viral infections (continued). "Following Tyk2 shRNA‐mediated knockdown, there was reduced expression of Tyk2 by western blot compared to control shLacZ virus infection, as well as decreased expression at an mRNA level." (PMID 31278855, 2019). "Consistent with this, pancreatic islets of MIP-Tyk2 Tg Tyk2 KO mice remained histologically intact with minimal destructive changes after viral infection compared with extensive damaged islets in Tyk2 KO mice." (PMID 25849081, 2015). "Interferon-regulatory factors and interferon receptor-associated downstream molecules including JAK1, TYK2, STAT1 and STAT2 are also important with respect to serving as resistance against viral infections." (PMID 26288847, 2015). "Patients with autosomal recessive hyper IgE syndrome lack the connective tissue and skeletal manifestations, but an increased rate of viral infections (DOCK8 mutations) and intracellular bacteria (TYK2 mutations)." (PMID 25379309, 2014). "The fact that the heterozygous parents of these individuals are healthy, however, is encouraging, and partial reduction of TYK2 via viral infection of Tyk2 shRNA was sufficient to reduce tau levels and mitigate astrogliosis and microgliosis seen in tauopathy mouse models." (PMID 39528671, 2024). "Additionally, TYK2 knock-out mice pretreated with type III IFN prior to influenza infection were protected against viral infection in respiratory epithelial cells, while type I IFN pretreatment did not confer protection (unpublished)." (PMID 33362795, 2020). "Several mutations in the Tyk2 locus have been identified in patients, however they do not show a high susceptibility to viral infections." (PMID 33362795, 2020). "More recently, another report of seven TYK2-deficient patients has shown that the core clinical phenotype of TYK2 deficiency is due to mycobacterial and/or viral infections and not to HIES14." (PMID 29725107, 2018). "As an example, the first patient in whom a mutation in TYK2 (member of the JAK family of tyrosine kinases) was identified was diagnosed with hyper-IgE syndrome accompanied by lesions of the skin, BCG disease, as well as fungal and viral infections." (PMID 29230214, 2017). "TYK2 promoter variant did not affect IgE value, but it was most likely associated with viral infections in diabetic patients dependent on mildly defective IFN response." (PMID 28826655, 2017). "To test whether signaling from Ifnar1 was necessary for the induction of Ch25h during viral infection, we next conducted de novo synthesis experiments in Tyk2−/− macrophage cells." (PMID 23273843, 2013). "This situation can readily be observed in deficiencies of STAT2, TYK2, IFNAR1, and IFNAR2, in which severe viral disease affects some but not all individuals, with a greater penetrance observed for infections with live-attenuated viral vaccines than for common viral infections of childhood." (PMID 41608500, 2025). "However, TYK2 deficiency as a genetic cause of HIES remains controversial, since TYK2 deficient patients presenting with mycobacterial and viral infections in the absence of HIES have been reported." (PMID 30671054, 2018). "Overexpression of JAK1, TYK2, MAP2K1, IFNG, TRPM2, and ADCY9 significantly inhibited viral infection, whereas overexpression of SNX27, GATA4, EHMT2, PCBP2, SMARCA4, and SLX4 enhanced viral infection." (PMID 40530850, 2025). "TYK2 also interacts with STAT3, which is vital to virus infection." (PMID 37371627, 2023). "Human cells homozygous for rare loss-of-expression (LOE) TYK2 alleles have impaired, but not abolished, cellular responses to IFN-α/β (underlying viral diseases in the patients) and to IL-12 and IL-23 (underlying mycobacterial diseases)." (PMID 36094518, 2022). "Interferons are normally produced and secreted upon viral infection, and secreted IFN binds to the IFN receptor and activates Janus kinase 1 (JAK1) and tyrosine kinase 2 (TYK2) which phosphorylate signal transducers and activators of transcription proteins (STAT1 and STAT2)." (PMID 36091073, 2022).
viral infections (continued). "Tyk2 KO mice were shown to have defective IFN-I and IL-12 responses, and were susceptible to viral infection, albeit not as severely as IFNAR1 KO mice." (PMID 34290741, 2021). "Further investigation showed that the lack of TYK2 impacted the ability of type I IFNs to clear viral infection while type III IFNs maintained their antiviral capacities showing that TYK2 is dispensable for the type III IFN mediation signaling of IL-10R2." (PMID 30901970, 2019). "TYK2-HIES does not have development of pneumatoceles and both forms are distinct given their susceptibility to viral infections such as herpes and molluscum contagiosum." (PMID 22126402, 2011). "- AR complete TYK2 deficiency (with or without TYK2 expression): Characterized by MSMD (and more rarely tuberculosis) and/or viral diseases due to an impaired response to IL-12, IL-23 (poor IFN-γ underlies mycobacterial diseases), IFN-α (viral diseases), and IL-10 signaling." (PMID 41438753, 2025). "Given that key mediators of IFN-I signaling are located in the plasma membrane (e.g., IFNAR1, Tyk2), it is possible that CD24 expression alters the composition or structure of key sites within the plasma membrane, which indirectly alters steps in IFN-I responses to virus infections." (PMID 36016357, 2022). "Two types of inherited TYK2 deficiencies are known: AR complete deficiency underlying MSMD (and more rarely TB) and/or viral diseases, and homozygosity for P1104A deficiency underlying TB (and more rarely MSMD) without viral diseases." (PMID 36094518, 2022). "To further determine the impact of IFN signaling on the resistance of H820 cells to viral infection, we treated these cells with a non-cytotoxic concentration of ruxolitinib (JAK and Tyk2 inhibitor) and infected them with influenza A virus." (PMID 40434103, 2025). "Somewhat surprisingly given the partnership of JAK1 with TYK2 for IFN-α/βR signaling, serious viral infections were not seen." (PMID 36159783, 2022).